OR52N4 (olfactory receptor family 52 subfamily N member 4)
Description:
Odorant receptor.
Synonyms: OR11-64
Tractability: Antibody: UniProt places it where antibodies can reach, with medium confidence; UniProt predicts a signal peptide or a membrane-spanning region; its Gene Ontology location is reachable by antibodies, with medium confidence.
Gene: Protein-coding gene on chromosome 11 (5,754,243 to 5,755,958, forward strand). Ensembl gene ENSG00000181074.
Subcellular location: Cell membrane
Pathways (Reactome):
Sensory Perception: Expression and translocation of olfactory receptors
Gene Ontology:
Molecular function: olfactory receptor activity; G protein-coupled receptor activity
Biological process: detection of chemical stimulus involved in sensory perception of smell; G protein-coupled receptor signaling pathway; nervous system process
Cellular component: plasma membrane; membrane
Genetic constraint (gnomAD): Loss-of-function variants: 15 observed, 15.77 expected, observed/expected ratio (o/e) 0.95, 90% interval 0.63 to 1.46. The upper end of that interval is the gene's LOEUF score, 1.46, which puts it in group 6 of 6, group 1 being the genes least tolerant of losing a copy. Missense variants: 421 observed, 415.43 expected, observed/expected ratio (o/e) 1.01, 90% interval 0.94 to 1.1. Synonymous variants: 143 observed, 146.24 expected, observed/expected ratio (o/e) 0.98, 90% interval 0.85 to 1.12.
Homologues: Orthologues: chimpanzee OR52N4 (98% identical), macaque OR52N4 (96% identical), mouse Or52n4 (88% identical), dog OR52N4F (85% identical), dog OR52N4G (83% identical), mouse Or52n4b (83% identical), rat Or52n4d (83% identical), rat Or52n4e (83% identical), dog OR52N4K (67% identical), tropical clawed frog or52ak1b (50% identical), tropical clawed frog or52ak1a (49% identical), tropical clawed frog or52k1 (49% identical), and 1 more. Paralogues in human: OR52N1 (72% identical), OR52N2 (72% identical), OR52N5 (67% identical), OR52R1 (52% identical), OR52E4 (51% identical), OR52K1 (50% identical), OR52L1 (50% identical), OR52A5 (50% identical), OR52E8 (50% identical), OR52E5 (50% identical), OR52E6 (49% identical), OR52K2 (49% identical), and 39 more.
Diseases named in the same sentence as OR52N4 in open-access papers:
OR52N4 is named in the same sentence as 1 disease in open-access papers, as found by Europe PMC text mining. Sharing a sentence is not in itself a finding about the gene and the disease.
OR52N4 shares sentences with these, for which no sentence is quoted: breast carcinoma (1 paper).